RNU6-106P (RNA, U6 small nuclear 106, pseudogene)
Gene: Small nuclear RNA gene on chromosome 1 (155,358,712 to 155,358,818, reverse strand). Ensembl gene ENSG00000207134.
Homologues: Orthologues: chimpanzee U6 (97% identical), macaque U6 (94% identical). Paralogues in human: RNU6-1152P (91% identical), RNU6-1181P (90% identical), RNU6-16P (89% identical), RNU6-393P (89% identical), RNU6-41P (89% identical), RNU6-1145P (88% identical), RNU6-12P (88% identical), RNU6-13P (88% identical), RNU6-32P (88% identical), RNU6-35P (88% identical), RNU6-434P (88% identical), RNU6-968P (88% identical), and 1284 more.